RNU2-41P (RNA, U2 small nuclear 41, pseudogene)
Gene: Small nuclear RNA gene on chromosome 2 (114,420,125 to 114,420,302, forward strand). Ensembl gene ENSG00000222923.
Homologues: Orthologues: chimpanzee U2 (85% identical), rabbit U2 (46% identical), mouse Gm22984 (44% identical), pig U2 (44% identical), dog U2 (35% identical), rat LOC120097279 (34% identical), guinea pig U2 (31% identical). Paralogues in human: RNU2-72P (47% identical), RNU2-58P (46% identical), RNU2-22P (45% identical), RNU2-10P (43% identical), RNU2-53P (43% identical), RNU2-24P (41% identical), RNU2-16P (40% identical), RNU2-28P (40% identical), RNU2-55P (39% identical), RNU2-60P (39% identical), RNU2-12P (37% identical), RNU2-42P (37% identical), and 63 more.